WDR45B (WD repeat domain 45B)
Description:
Component of the autophagy machinery that controls the major intracellular degradation process by which cytoplasmic materials are packaged into autophagosomes and delivered to lysosomes for degradation. Binds phosphatidylinositol 3-phosphate (PtdIns3P), and other phosphoinositides including PtdIns(3,5)P2, forming on membranes of the endoplasmic reticulum upon activation of the upstream ULK1 and PI3 kinases and is recruited at phagophore assembly sites where it regulates the elongation of nascent phagophores downstream of WIPI2. In the cellular response to starvation, may also function together with the TSC1-TSC2 complex and RB1CC1 in the inhibition of the mTORC1 signaling pathway.
Synonyms: WIPI-3; WDR45L; WIPI3; NEDSBAS
Tractability: PROTAC: ubiquitination databases record sites on it; its protein half-life has been measured.
Gene: Protein-coding gene on chromosome 17 (82,614,562 to 82,648,553, reverse strand). Ensembl gene ENSG00000141580.
Subcellular location: Preautophagosomal structure; Lysosome
Subcellular location (Human Protein Atlas): Golgi apparatus; Cytosol; Nucleoplasm
Pathways (Reactome):
Autophagy: Macroautophagy
Gene Ontology:
Molecular function: phosphatidylinositol-3,5-bisphosphate binding; phosphatidylinositol-3-phosphate binding; protein binding; TSC1-TSC2 complex binding; protein-macromolecule adaptor activity
Biological process: autophagosome assembly; cellular response to starvation; autophagy of mitochondrion; glycophagy; nucleophagy; pexophagy; protein localization to phagophore assembly site
Cellular component: cytosol; lysosome; phagophore assembly site; phagophore assembly site membrane
Genetic constraint (gnomAD): Loss-of-function variants: 20 observed, 45.86 expected, observed/expected ratio (o/e) 0.44, 90% interval 0.31 to 0.63. The upper end of that interval is the gene's LOEUF score, 0.63, which puts it in group 2 of 6, group 1 being the genes least tolerant of losing a copy. Missense variants: 323 observed, 445.37 expected, observed/expected ratio (o/e) 0.73, 90% interval 0.66 to 0.8. Synonymous variants: 169 observed, 171.31 expected, observed/expected ratio (o/e) 0.99, 90% interval 0.87 to 1.12.
Homologues: Orthologues: chimpanzee WDR45B (100% identical), guinea pig WDR45B (100% identical), macaque WDR45B (100% identical), mouse Wdr45b (99% identical), rat Wdr45b (99% identical), pig WDR45B (99% identical), tropical clawed frog wdr45b (97% identical), zebrafish wdr45b (96% identical), dog WDR45B (93% identical), rabbit WDR45B (85% identical), Drosophila melanogaster CG11975 (67% identical). Paralogues in human: WDR45 (50% identical), WIPI2 (31% identical), WIPI1 (30% identical).
Diseases named in the same sentence as WDR45B in open-access papers:
WDR45B is named in the same sentence as 29 diseases in open-access papers, as found by Europe PMC text mining. Sharing a sentence is not in itself a finding about the gene and the disease. The quoted sentences say what the papers report.
Intellectual disability (5 papers, 2020 to 2024). "In addition, WDR45B is associated in humans with a neurodevelopmental syndrome characterized by spastic quadriplegia, epilepsy, intellectual disability, and cerebral hypoplasia." (PMID 35252421, 2022). "Defects in WIPI2 cause a disease characterized mainly by intellectual disability and variable other features while pathogenic variants in WDR45B and WDR45 have been recently reported to cause El-Hattab-Alkuraya syndrome and beta-propeller protein-associated neurodegeneration (BPAN), respectively." (PMID 36157071, 2022). "Mutations in WDR45B and WDR45 lead to β-propeller protein-associated neurodegeneration and intellectual disability, respectively." (PMID 36900050, 2023).
asthma (2 papers, 2021 to 2023). "Given the hypothesized link between asthma pathogenesis and autophagy, we sought to identify whether the autophagy‐promoting gene products of WD repeat domain 45B (WDR45B) were involved in GLCCI1 modulation of asthma susceptibility and treatment response." (PMID 34050597, 2021). "Recently, WDR45B was found to improve airway remodeling and reduce collagen deposition and airway hyperreactivity in mouse asthma models, by means of combining with glucocorticoid induced 1 (GLCCI1) to inhibit the autophagy activation effect of GLCCI1." (PMID 36900050, 2023). "Increasing of WDR45B in vivo reversed the improvement of GLCCI1 on airway remodelling in asthma and the inhibition to autophagy level in lung tissues." (PMID 34050597, 2021). "In this present study, we explored the mechanism of GLCCI1 in regulating asthma development through activation autophagy via binding with WDR45B." (PMID 34050597, 2021). "Overall, our data indicated that GLCCI1 could effectively improve the airway remodelling in ovalbumin‐sensitized mice through inhibiting asthma‐induced autophagy via combination with WDR45B and suppressing its expression." (PMID 34050597, 2021).
El-Hattab-Alkuraya syndrome (2 papers, 2022 to 2023). "Mutations in WDR45B, which encodes WIPI3, also cause a complex neurodevelopmental disorder called El-Hattab-Alkuraya syndrome (OMIM#617977), while mutations in WIPI2 cause a neurodevelopmental disorder accompanied by skeletal and cardiac abnormalities (OMIM#618453)." (PMID 37364041, 2023).
microcephaly (2 papers, 2021 to 2022). A congenital or acquired developmental disorder in which the circumference of the head is smaller than normal for the person's age and sex. "Six years later, an additional individual with GDD and microcephaly with a homozygous nonsense variant in WDR45B was identified." (PMID 36157071, 2022).
Cirrhosis (1 paper, 2023). A chronic disorder of the liver in which liver tissue becomes scarred and is partially replaced by regenerative nodules and fibrotic tissue resulting in loss of liver function. "The correlation between WDR45B expression level and clinical pathological characteristics including age, sex, T stage, macroscope vein invasion, microvascular invasion, cirrhosis, tumor involvement, and Alpha-fetoprotein (AFP) IHC staining was analyzed by chi-square test." (PMID 36900050, 2023). "Based on the detailed clinical traits of HCC patients in TCGA cohorts involving age, sex, cirrhosis scores, grade, TNM stage, vascular invasion, and adjacent inflammation from UCSC Xena, the correlation between expression level of WDR45B and clinical traits was analyzed." (PMID 36900050, 2023).
Dyskinesia (1 paper, 2023). A movement disorder which consists of effects including diminished voluntary movements and the presence of involuntary movements. "WDR45B-knockout mice showed dyskinesia, learning, and memory deficits." (PMID 36900050, 2023).
liver cancer (1 paper, 2023). An epithelial or non-epithelial malignant neoplasm that arises from the liver. "In research on thioacetamide mouse liver cancer model, CpG island hypermethylation of WDR45B and Yin Yang 1 (YY1) was observed in the pretumor liver disease foci of mice, which was involved in the regulation of cell cycle and apoptosis, promoting tumor formation." (PMID 36900050, 2023).
metastatic tumors (1 paper, 2024). "Collectively, we found that there is a large number of infiltrated immunosuppressive myeloid cells in PTs and MTs, and the SPP1+ and WDR45B+ TAMs may potentiate progression of primary and metastatic tumors in the liver." (PMID 38414027, 2024). "Based on these findings, we speculate that the increased autophagy levels in WDR45B+ TAMs may direct it towards M2 polarization, thereby facilitating the adaption and progression of metastatic tumors in the liver, which also needs to be confirmed in future study." (PMID 38414027, 2024).
scrapie (1 paper, 2022). A fatal disease of the nervous system in sheep and goats, characterized by pruritus, debility, and locomotor incoordination. "The fact that neuronal homeostasis and autophagy are dysregulated in scrapie could possibly explain the WDR45B upregulation observed in naturally infected scrapie animals." (PMID 35252421, 2022). "Of all the selected genes, significant changes between the control and scrapie animals were found in the expression of five genes: PCDH19, SNCG, WDR45B, PEX1, and CABIN1." (PMID 35252421, 2022). "WD repeat domain 45B (WDR45B/WIPI3) belongs to the WIPI protein family and was overexpressed in scrapie animals." (PMID 35252421, 2022). "We identified many DMRs between the control and scrapie animals, some of them belonging to genes with possible neuroprotective roles against neurodegeneration (SNCG and WDR45B) and to genes that may facilitate or contribute to scrapie disease progression (PCDH19, PEX1, and CABIN1)." (PMID 35252421, 2022).
Tinnitus (1 paper, 2020). Tinnitus is an auditory perception that can be described as the experience of sound, in the ear or in the head, in the absence of external acoustic stimulation. "Notably, we identified KCNN3, SOD3, MUC4, GALR1, and WDR45B, which are implicated in auditory function, as differentially methylated associated with self-reported tinnitus." (PMID 33192958, 2020). "Notably, tinnitus symptom analyses identified regions with differential methylation in genes KCNN3, MUC4, GALR1, SOD3, and WDR45B (in the low vs. high cumulative blast exposed groups." (PMID 33192958, 2020).
neurodevelopmental disorder (4 papers, 2021 to 2024). A behavioral and cognitive disorder with onset during the developmental period that involves impaired or aberrant development of intellectual, motor, or social functions. "In humans, homozygous variants in WDR45B are associated with a severe neurodevelopmental disorder with spastic quadriplegia and brain abnormalities with or without seizures (OMIM 617,977)." (PMID 38965607, 2024).
cancer (3 papers, 2020 to 2023). A tumor composed of atypical neoplastic, often pleomorphic cells that invade other tissues. "At present, the majority of studies about WDR45B almost all focused on neuronal degeneration diseases, while very few on the aspect of cancer." (PMID 36900050, 2023). "Therefore, this study was dedicated to the potential cancer-promoting mechanism of WDR45B in HCC, hoping to bring new strategies for the diagnosis and treatment of HCC." (PMID 36900050, 2023).
neurodegenerative disease (2 papers, 2020 to 2022). A disorder of the central nervous system characterized by gradual and progressive loss of neural tissue and neurologic function. "Three proteins, WIPI2, WDR45B, WDR45, are already associated with Mendelian neurodegenerative diseases." (PMID 36157071, 2022).
tumor (2 papers, 2023 to 2024). "With regard to myeloid cells, the liver-resident macrophages and inflammatory monocyte/macrophages were markedly replaced by tumor-associated macrophages (TAMs), with TREM2+ and UBE2C+ TAMs enriched in PTs, while SPP1+ and WDR45B+ TAMs in MTs." (PMID 38414027, 2024). "Next, we explored the unique function of WDR45B+ TAMs compared to the other TAMs, and found upregulation of several known tumor-promoting genes, such as LGALS2 and GPR183." (PMID 38414027, 2024). "The expression levels of WDR45B in tumor tissues and adjacent normal tissues from TCGA were compared in total and in pairs." (PMID 36900050, 2023). "Representative histological images of 4×, 10×, and 20× magnifications were exhibited to visualize the WDR45B expression in tumor and normal liver tissues." (PMID 36900050, 2023). "In vitro experiments showed that the knockdown of WDR45B can suppress autophagy by upregulating the Akt/mTOR signaling pathway and reduce tumor proliferation and migration." (PMID 36900050, 2023). "It suggested that WDR45B was overexpressed in tumor tissues." (PMID 36900050, 2023).
infection (1 paper, 2021). The state of being infected such as from the introduction of a foreign agent such as serum, vaccine, antigenic substance or organism. "Our results showed that the expression of WDR45B can be significantly increased by LV‐WDR45B infection." (PMID 34050597, 2021).
WDR45B also shares sentences with these, for which no sentence is quoted: quadriplegia (2 papers); Cerebellar atrophy (1); cerebellar degeneration (1); developmental delay (1); Encephalopathy (1); epilepsy (1); hearing loss (1); hepatocellular carcinoma (1); liver disease (1); neuroblastoma (1); Obesity (1); prostate carcinoma (1); prostate tumor (1); thymoma (1).